NARF-IT1 (NARF intronic transcript 1)
Synonyms: formerly NARF-OT1
Gene: Long non-coding RNA gene on chromosome 17 (82,482,098 to 82,483,388, forward strand). Ensembl gene ENSG00000266236.
Diseases named in the same sentence as NARF-IT1 in open-access papers:
NARF-IT1 is named in the same sentence as 1 disease in open-access papers, as found by Europe PMC text mining. Sharing a sentence is not in itself a finding about the gene and the disease. The quoted sentences say what the papers report.
acute monocytic leukemia (1 paper, 2022). Acute monoblastic leukemia (AML-M5), is one of the most common subtypes of acute myeloid leukemia (AML) that is either comprised of more than 80% of monoblasts (AML-M5a) or 30-80% monoblasts with (pro)monocytic differentiation (AML-M5b). "Finally, we verified the expression levels of CRNDE, CHROMR and NARF-IT1 in ML cell lines K562, MOLM13 and acute monocytic leukemia cell line THP-1, which were significant." (PMID 34996458, 2022).